NAT1 (N-acetyltransferase 1)
Description:
Participates in the detoxification of a plethora of hydrazine and arylamine drugs. Catalyzes the N- or O-acetylation of various arylamine and heterocyclic amine substrates and is able to bioactivate several known carcinogens.
Synonyms: MNAT; NAT-1; AAC1; NATI
Tractability: Small molecule: a high-quality ligand is known; it has a high-quality binding pocket; it belongs to a druggable protein family. PROTAC: ubiquitination databases record sites on it; its protein half-life has been measured; a small molecule that binds it is known.
Target class: Enzyme; Transferase
Gene: Protein-coding gene on chromosome 8 (18,170,399 to 18,223,739, forward strand). Ensembl gene ENSG00000171428.
Subcellular location: Cytoplasm
Pathways (Reactome):
Drug ADME: Paracetamol ADME
Metabolism: Acetylation
Gene Ontology:
Molecular function: N-hydroxyarylamine O-acetyltransferase activity; protein binding; arylamine N-acetyltransferase activity; protein-cysteine S-acyltransferase activity; acetyltransferase activity
Biological process: xenobiotic metabolic process
Cellular component: cytosol; cytoplasm
Genetic constraint (gnomAD): Loss-of-function variants: 1 observed, 0.84 expected, observed/expected ratio (o/e) 1.19, 90% interval 0.29 to 1.91. That is too few expected variants to judge how well the gene tolerates losing a copy. Missense variants: 400 observed, 357.18 expected, observed/expected ratio (o/e) 1.12, 90% interval 1.03 to 1.22. Synonymous variants: 144 observed, 129.17 expected, observed/expected ratio (o/e) 1.11, 90% interval 0.97 to 1.28.
Homologues: Orthologues: chimpanzee NAT1 (98% identical), macaque NAT1 (95% identical), mouse Nat2 (82% identical), rat Nat3 (82% identical), guinea pig Nat1 (81% identical), rat Nat2 (76% identical), mouse Nat1 (75% identical), mouse Nat3 (68% identical), rat Nat3 (68% identical), zebrafish si:dkey-78a14.4 (43% identical), zebrafish zgc:101040 (40% identical). Paralogues in human: NAT2 (81% identical).
Diseases named in the same sentence as NAT1 in open-access papers:
NAT1 is named in the same sentence as 72 diseases in open-access papers, as found by Europe PMC text mining. Sharing a sentence is not in itself a finding about the gene and the disease. The quoted sentences say what the papers report.
breast carcinoma (48 papers, 2008 to 2025). "Further, the inhibition or loss of NAT1 results in a loss of the ability of breast cancer cells to grow in an anchorage-independent manner (growth in soft agar)." (PMID 37107601, 2023). "Several reports have demonstrated the upregulation of NAT1 in breast cancer is associated with estrogen receptor (ER) expression." (PMID 35153780, 2022). "Arylamine N-acetyltransferase 1 (NAT1) is a drug metabolising enzyme that has been associated with increased survival in breast cancer patients." (PMID 35918499, 2022). "In summary, the current study has shown that loss of NAT1 in breast cancer cells is likely to enhance drug resistance by inhibiting intrinsic apoptosis, possibly leading to the activation of necroptosis as the major cell death pathway." (PMID 35918499, 2022). "Histone deacetylation and DNA methylation at CpG islands constitute another layer of epigenetic regulation of gene expression; methylation of the 5′-untranslated region of NAT1 has been linked associated to tamoxifen-resistant breast cancer tumors." (PMID 35153780, 2022). "The current study aimed to investigate drug resistance in vitro using normal breast cancer cell lines and NAT1-deficient cell lines to understand the changes induced by the lack of NAT1 that resulted in poor drug response." (PMID 35918499, 2022). "The loss of NAT1 increased SNAIL expression in a range of breast cancer cells, whereas both N-cadherin and β-catenin were reduced." (PMID 35918499, 2022). "The results of the present study show that NAT1 deficiency in breast cancer cells increased resistance to a range of chemotherapeutic agents regardless of their mechanism of action." (PMID 35918499, 2022). "There is a strong association between estrogen receptor positive breast cancer and high NAT1 expression." (PMID 35046826, 2021). "Reducted arylamine N-acetyltransferase (NAT1) in breast cancers is associated with poor patient survival." (PMID 31910058, 2020). "To focus on metabolome differences associated with varying levels of NAT1 in breast cancer, we have focused our interpretation of this study to metabolites that agreed between the two CRISPR NAT1 KO cell lines." (PMID 32555504, 2020). "Next to its association with survival of breast epithelial cells, NAT1 has been proposed as a useful biomarker for breast cancer." (PMID 30610490, 2019). "The most striking examples were seen in breast cancer array data where NAT1 up-regulation was commonly associated with estrogen receptor (ER) positive tumors." (PMID 29969986, 2018). "The results of this study provide new evidence and insight into a role of rat NAT2 and, by analogy, human NAT1 in breast cancer susceptibility." (PMID 28359264, 2017). "In the present study, we have shown that downregulation of NAT1 in breast cancer cells results in a marked change in morphology, a loss of surface filopodia and a decrease in invasive potential both in vitro and in vivo." (PMID 25627111, 2015). "Later studies showed that NAT1 is a potential biomarker for breast cancer 15 and higher expression is associated with increased disease mortality and recurrence." (PMID 25627111, 2015). "Kaplan-Meier analysis showed that the presence of NAT1 was significantly associated with increased OS in breast cancer patients and with DFS and OS in patients who received adjuvant endocrine therapy with tamoxifen." (PMID 25528056, 2014). "A previous study revealed that the relationship between smoking and risk of breast cancer was modified by the NAT1 or NAT2 genotype among postmenopausal women." (PMID 24204725, 2013). "NAT1 genetic polymorphisms were also considered to be sensitive to smoking history in the etiology of breast cancer." (PMID 24204725, 2013). "Moreover, NAT1, whose overexpression is linked to carcinogenesis, especially breast cancer, was also highly abundant in cyclophosphamide-resistant cell lines." (PMID 41301803, 2025).
breast carcinoma (continued). "NAT1 has also been implicated in breast cancer progression however the exact role of NAT1 remains unknown." (PMID 32555504, 2020). "The present population-based case-control study of breast cancer in Germany evaluated the role of genetic polymorphisms in Phase I and II enzymes NAT1 and NAT2 in the AA pathway and CYP1A1, CYP1B1, GSTM1 and GSTT1 in the PAH pathway and cigarette smoke exposure in breast carcinogenesis." (PMID 21080951, 2010). "The NAT1 gene, located on chromosome 8p22, encodes one of two human enzymes that are known to metabolize arylamine- and hydrazine-type drugs, and in this regard, a previous study has reported that low NAT1 expression resulted in a distinctly poor response to chemotherapy in breast cancer patients." (PMID 31781164, 2019). "Furthermore, our findings suggest that NAT1*10 human haplotypes may have a higher risk of breast cancer compared to the reference NAT1*4 haplotype." (PMID 28359264, 2017). "Thus, miR-1290 and its target NAT1 are associated with important characteristics of breast cancer." (PMID 25528056, 2014). "Thus, miR-1290 and its potential target NAT1 are associated with characteristics of breast cancer." (PMID 25528056, 2014). "Studies have shown that NAT1 inhibits the glycolytic capacity of breast cancer cells, thus suppressing their occurrence, development, and metastasis." (PMID 38916406, 2024). "The expression of NAT1 varies among individuals and is typically reduced in various cancers, including estrogen receptor-positive (ER+) breast cancer and colorectal cancer." (PMID 38916406, 2024). "NAT1 is a metabolic enzyme that has been investigated in relation to breast cancer energy metabolism." (PMID 38916406, 2024). "Examinations into the role of NAT1 in breast cancer cellular energetics have also been investigated." (PMID 37107601, 2023). "Our results further support the literature that NAT1 KO in breast cancer cells alters their cellular metabolism." (PMID 37107601, 2023). "NAT1 KO in MDA-MB-231 breast cancer cells reduced anchorage-independent colony formation and primary and secondary tumors in immunocompromised mice." (PMID 37107601, 2023). "It has been shown that NAT1 regulates the function of matrix metalloproteinase 9 (MMP9) in breast cancer cell models and protects from reactive oxygen species (ROS) during the shortage of glucose." (PMID 37469704, 2023). "Further, the present study demonstrated that NAT1 KO in breast cancer cells (MDA-MB-231) resulted in an altered fate in the metabolism of glucose." (PMID 37107601, 2023). "Studies have utilized both small molecule-mediated inhibition and CRISPR/Cas9 NAT1 KO to investigate the role of NAT1 in breast cancer cell lines." (PMID 37107601, 2023). "Multiple independent research groups have reported that inhibition of NAT1 in various breast cancer cell lines resulted in a changed mitochondrial respiration response." (PMID 37107601, 2023). "The metabolism changes in the fate of glucose in NAT1 KO breast cancer cells offer more insight into the role of NAT1 in energy metabolism and the growth of breast cancer cells." (PMID 37107601, 2023). "To investigate the metabolic changes to glucose utilization following NAT1 KO in breast cancer cells, we used [U-13C]-glucose tracer studies." (PMID 37107601, 2023). "Recently, the knockdown of NAT1 utilizing CRISPR/Cas9 in MDA-MB-231 breast cancer cell lines impacted the cellular metabolism depending upon its expression level." (PMID 37469704, 2023). "In this current study, we used [U-13C]-glucose stable isotope resolved metabolomics to determine the effect of NAT1 KO on the metabolic profile of MDA-MB-231 breast cancer cells." (PMID 37107601, 2023). "Previous publications have established that NAT1 knockout (KO) in breast cancer cell lines leads to growth reduction both in vitro and in vivo and metabolic changes." (PMID 37107601, 2023).
breast carcinoma (continued). "This upregulation of NAT1 in breast cancers led to investigations into understanding the role of NAT1 in cancer cell energetics, cell growth, and cell morphology." (PMID 37107601, 2023). "Although there have been some discrepancies reported between studies, there is consensus that NAT1 inhibition or NAT1 KO in cultured breast cancer cells results in cell growth retardation and reduced migration/invasion." (PMID 37107601, 2023). "It is a possibility that, while high NAT1-expressing breast cancers present a more aggressive phenotype, they are easier to treat with conventional methods that target cells undergoing rapid proliferation." (PMID 35918499, 2022). "Several different studies have demonstrated that NAT1 is overexpressed in breast cancer, suggesting that it plays an important role in breast cancer development and growth." (PMID 35153780, 2022). "For example, low NAT1 expression is associated with enhanced docetaxel and doxorubicin resistance in PC3 prostate cancer cells and MCF-7 breast cancer cells, respectively." (PMID 35918499, 2022). "Arylamine N-acetyltransferase 1 (NAT1) is a drug metabolizing enzyme that influences cancer cell proliferation and survival, especially in breast cancer." (PMID 35153780, 2022). "In the present study, we investigated the contribution of Lysine deacetylases (KDAC) in the catalytic activity of NAT1 using two different breast cancer cell lines: MDA-MB-231 (ER-, PR-, HER2-) and ZR-75-1 (ER+, PR+, HER2+)." (PMID 35153780, 2022). "We investigated the effect that Lysine-acetylation, as a post-translational modification (PTM), has on the catalytic activity of NAT1 in two different breast cancer cell lines, MDA-MB-231 and ZR-75-1." (PMID 35153780, 2022). "Using mRNA sequencing and proteomic data from TCGA and CPTAC of 24 different solid tumors, we identified six potential genes that are specifically upregulated in breast carcinoma: NAT1, MGP, SCGB2A2, LMX1B, TFAP2B, and TRPS1." (PMID 36284362, 2022). "NAT1 is differentially expressed in breast cancer subtypes, being highest in those of luminal origin and lowest in basal-like tumours." (PMID 35918499, 2022). "A previous study has reported that low NAT1 expression resulted in a distinctly poor response to chemotherapy in breast cancer patients." (PMID 36727052, 2022). "Arylamine N-acetyltransferase 1 (NAT1) deficiency has been associated with drug resistance and poor outcomes in breast cancer patients." (PMID 35918499, 2022). "Seven different drugs were investigated in four breast cancer cell lines – triple negative MDA-MB-231 cells, estrogen receptor positive T-47D cells, NAT1 deficient MDA-MB-231 cells and NAT1 deficient T47D cells." (PMID 35918499, 2022). "The aim of the present work is to investigate the acetylation status of NAT1 in human breast cancer." (PMID 35153780, 2022). "A study of almost 2000 breast cancer patients found the presence of three genetically distinct populations based on NAT1 expression alone." (PMID 35918499, 2022). "This is the first study to measure the global transcriptome profile of breast cancer cells with varying levels of NAT1 N-acetylation activity." (PMID 35046826, 2021). "Another study proposed that microRNA-6477-5p increased anoikis sensitivity by targeting NAT1 (an important paralog of NAT2) in breast cancer." (PMID 34867333, 2021). "In fact, the overexpression of miR-6744-5p increases the sensitivity of breast cancer cells to anoikis, along with the abatement of invasion and metastasis capabilities, via targeting NAT1." (PMID 33435156, 2021). "Many cancers, including breast cancer, have shown differential expression of human arylamine N-acetyltransferase 1 (NAT1)." (PMID 35046826, 2021). "Particularly, the negative association between the genes CDH2, CDH3, CDH11, CDH13, CDH18 and NAT1 N-acetylation activity supports observations of high NAT1 expression in breast cancer and increased metastasis." (PMID 35046826, 2021).
breast carcinoma (continued). "Our objective is to further evaluate the role of NAT1 in breast cancer by determining the effect of NAT1 overexpression, knockdown, and knockout on global gene expression in MDA-MB-231 cell lines." (PMID 35046826, 2021). "Although the mechanism by which NAT1 depletion leads to an alteration of the pyrimidine biosynthetic pathway is currently unclear, the present observation has an implication in breast cancer therapy." (PMID 32555504, 2020). "A better understanding of the role NAT1 has in breast cancer would aide in the development of novel treatment strategies and therapeutics." (PMID 32555504, 2020). "The overexpression of this miRNA, miR-6744-5p promotes anoikis in both luminal A and triple negative breast cancer cell lines, and miR-6744-5p directly target NAT1 enzyme, indicating its potential in breast cancer therapeutics and prognostics." (PMID 32296579, 2020). "Other studies have attempted knockdown of NAT1 enzyme in breast cancer cells, producing comparably identical in vitro results to that seen during the overexpression of miR-6744-5p in MDA-MB-2319." (PMID 32296579, 2020). "Research on breast cancer and NAT1 enzyme has only begun to gain momentum, and it is expected that NAT1’s role as an oncogene will achieve further clarification in the near future." (PMID 32296579, 2020). "Endo and colleagues have published their findings and validation of miR-1290 targeting NAT1 enzyme using ER α-positive breast cancer tissue samples." (PMID 32296579, 2020). "In breast cancer, NAT1 expression is inversely related to overall survival and predicts response to cytotoxic chemotherapy but not hormonal therapy." (PMID 31910058, 2020). "Some polymorphism of arylamine N-acetyltransferases types 1 and 2 (NAT1, NAT2) confer a higher risk of developing breast cancer." (PMID 32085420, 2020). "For example, in breast cancer, NAT1 expression is downregulated in young patients (≤45 years) compared with that in old patients, whereas NTA1 presents overexpressed in estrogen receptor-positive cancer in comparison of estrogen receptor-negative cancer." (PMID 32793479, 2020). "NAT1 activity varies inter-individually and has been shown to be overexpressed in estrogen receptor-positive (ER+) breast cancers." (PMID 32555504, 2020). "In breast cancer, survival is significantly better in those patients with high tumor NAT1 expression compared to those with low tumor NAT1 expression." (PMID 31910058, 2020). "In support of this notion, we found that NAT1 KO reduced anchorage-independent growth in all three breast cancer cell lines tested." (PMID 31531019, 2019). "Depletion of NAT1 in ZR-75-1 cells did not result in an increase in the AcCoA level despite the fact that they exhibit the highest NAT1 activity among the three breast cancer cell lines tested." (PMID 31531019, 2019). "In conclusion, we knocked out human NAT1 with CRISPR/Cas9 technology using two different gRNA's in three different breast cancer cells lines." (PMID 31531019, 2019). "We investigated the effect of NAT1 gene deletion in three different human breast cancer cell lines, MDA-MB-231, MCF-7, and ZR-75-1." (PMID 31531019, 2019). "In breast cancer, NAT1 mRNA in each sub-population correlated with a separate set of genes suggesting different mechanisms of NAT1 gene regulation." (PMID 29969986, 2018). "It would be interesting to correlate mir-1290 expression with that for NAT1, especially in the intermediate breast cancer group." (PMID 29969986, 2018). "NAT1 is significantly elevated and correlates with epithelial to mesenchymal activation in breast cancer bone metastasis." (PMID 29518119, 2018). "This is consistent with the increase in bone metastasis for breast carcinomas expressing high levels of NAT1 mRNA." (PMID 29969986, 2018). "This is the first study to specifically examine the distribution of NAT1 mRNA in primary breast cancers from a well-characterized and extensively studied patient cohort." (PMID 29969986, 2018).